MSI2 (musashi RNA binding protein 2)
Diseases named in the same sentence as MSI2 in open-access papers (continued):
Sharing a sentence is not in itself a finding about the gene and the disease.
cancer (continued). "Musashi-2 (MSI2) and its homolog, MSI1, are emerging as regulators of multiple critical biological processes relevant to cancer initiation, progression, stem cell compartment maintenance, and drug resistance, which are upregulated in many hematopoietic and solid tumors, including lung." (PMID 33723247, 2021). "Considering the golden standard in defining a drug’s putative target is that the depletion of a target confers resistance to the drug; it is essential to identify small molecules specifically sensitive to the wild-type (WT) but not MSI2-depleted cancer cells." (PMID 35153752, 2021). "A large proportion (47 RBPs) are commonly regulated in both RSCC and LSCC with several enriched for binding among DEGs (adj p < 0.05), including RBPs previously discussed in the context of CRC such MSI2, MEX3A, IGF2BP1/3, ELVAL4, and cancers in general, such as RBM47, DKC1, CELF4, ELAVL3." (PMID 32293332, 2020). "Notably, although MSI2 regulates tumor growth in various cancers, our findings demonstrate that the circPRKD3–MSI2 axis specifically enhances metastatic capacity without affecting proliferation in PDAC." (PMID 41049614, 2025). "It is possible that MSI2 may act in concert with these factors by regulating TIC self-renewal with the maintenance of an undifferentiated gene expression program in HCC, thus contributing to the poor clinical outcome of such cancers." (PMID 37117191, 2023). "The C‐terminal region of MSI2 has no known motifs or specific function, while the N‐terminal RRMs mediate the binding to mRNAs,25 including those involved in the proliferation of certain cancers." (PMID 31603583, 2020).
tumor (72 papers, 2012 to 2026). "In colon adenomas driven by APC loss-of-function mutations, MSI2 acts as an inhibitor of known tumor suppressors, including LRIG1, BMPR1A, CDKN1A, and PTEN and sustained activation of mTORC1." (PMID 41498402, 2026). "In colon adenomas driven by APC loss of function mutations, MSI2 acts as an inhibitor of known tumor suppressors including Lrig1, Bmpr1a, Cdkn1a, and Pten and sustained activation of mTORC116." (PMID 38234720, 2023). "The potential role of MSI2 in aggressive tumors has been suggested, attributable to its elevated expression in tumor tissues, which is often positively associated with tumor size, chemotherapy resistance, and metastasis." (PMID 37941042, 2023). "In studies using multiple mouse models for CRC formation, MSI2 overexpression was shown to inhibit expression of tumor suppressors, partially phenocopying changes induced by loss of APC." (PMID 34237057, 2021). "Meanwhile, high MSI2 expression was positively associated with tumor size and UICC stage in PC patients, whereas Numb positive expression was negatively associated with tumor size, UICC stage and differentiation." (PMID 27092875, 2017). "The alternatively spliced Msi2 variant 2 is expressed more highly in SH-SY5Y tumor cells than in normal iPSCs suggesting an association between expression of Msi2 variant 2 and cell transformation." (PMID 28912529, 2017). "We also examined the consequences of knocking down MSI2 in GB tumor cells, because MSI2 was also identified as a SOX2-associated protein in U87 GB cells (Wilder and Rizzino, unpublished results)." (PMID 23667531, 2013). "(D) Loss of Msi2 consistently impairs tumor growth in flank transplants in vivo." (PMID 40047406, 2025). "Importantly, loss of Msi2 led to the formation of significantly fewer (84%) tumor lesions as well as a significantly lower (85%) overall tumor burden in the lung at a 14-week midpoint." (PMID 40047406, 2025). "(B) Loss of Msi2 significantly impairs tumor sphere formation in vitro (n = 3)." (PMID 40047406, 2025). "Hence, further investigation is required to elucidate the underlying mechanism of MSI2 in CRC tumor immunometabolism." (PMID 38347600, 2024). "Moreover, overexpression of MSI2 was associated with the aggressive proliferation of tumor xenografts." (PMID 37117191, 2023). "High MSI2 levels were associated with poor tumor differentiation, and poor prognosis." (PMID 37107676, 2023). "In addition, MSI2 positive expression was associated with certain phenotypes of tumor aggressiveness, such as clinical stage, depth of invasion, lymph node metastasis, liver metastasis and tumor size." (PMID 36530989, 2022). "Msi1 and Msi2 are shown to be associated with tumor initiation, progression, and drug resistance." (PMID 28753936, 2017). "Particularly, high MSI2 expression was positively associated with tumor size and UICC stage (P=0.004 and P=0.043, respectively), whereas Numb expression was negatively associated with tumor size, differentiation and UICC stage, respectively (P=0.009; P=0.002 and P=0.010, respectively)." (PMID 27092875, 2017). "Thus, knockdown of MSI2 causes both a large reduction in the growth of DAOY MB tumor cells and increases the expression of NUMB." (PMID 23667531, 2013). "Given the pathogenic roles of MSI2 in tumor progression, as well as the protective roles of HSPs in ferroptosis, we demonstrated that MSI2 could regulate multiple HSPs to repress ferroptosis, especially the ferroptosis suppressor genes HSPB1 and HSPA5, as evidenced by previous studies." (PMID 38041016, 2023). "Further, overexpression of an MSI2 transgene in bone marrow cells expressing BCR-ABL led to increased tumor burden." (PMID 41498402, 2026). "Here, we have used extensive genetic modeling and patient-derived xenografts (PDXs) to identify a dual role for Msi2: as a signal that acts initially to sensitize cells to transformation, and subsequently to drive tumor propagation." (PMID 40047406, 2025).
tumor (continued). "Enlarged mouse lungs with uneven morphology (metastatic nodules) were clearly observed in the Scr-treated clone #1 tumor-bearing group, whereas the number of nodules was reduced in the MSI2-knockdown group." (PMID 39990676, 2025). "Reduced Msi2 expression led to pronounced inhibition of tumor growth in two independent patient-derived xenografts." (PMID 40047406, 2025). "To understand the mechanism by which Msi2 impacts tumor growth, we knocked down Msi2 in KP cell lines and carried out an RNAseq analysis comparing control and knock-down cells." (PMID 40047406, 2025). "By inhibiting the translation of Numb, a protein that stimulates cell differentiation and functions as a tumor suppressor, Musashi2 (MSI2), an RNA-binding protein, controls stem cell maintenance and differentiation." (PMID 41221040, 2025). "MSI2’s transformative capacity is substantiated by its tumor-initiating potential in colorectal carcinogenesis, where its ectopic expression drives intestinal epithelial transformation in murine models." (PMID 41049614, 2025). "The Msi2-knockdown tumors had significantly reduced (89%) tumor cell numbers, indicating that established tumors remain dependent on Msi2 signaling for growth." (PMID 40047406, 2025). "Experiments in nude mice revealed that ELK4 silencing decreased tumor size, whereas MSI2 overexpression attenuated this inhibitory effect." (PMID 39969091, 2025). "Downstream analysis of genes involved in the migration of tumor cell lines revealed that MSI2 was the top regulator of migration, with a log ratio of 4.514, followed by MMP3, MMP1, and IL1β." (PMID 39990676, 2025). "Msi2 signaling emerges as a key dependency at initiation and continues to be needed during tumor progression." (PMID 40047406, 2025). "IHC staining of mouse lungs revealed upregulation of MSI2, vimentin, and N-cadherin and downregulation of E-cadherin in the Scr-treated clone #1 tumor-bearing group, whereas these changes were reversed when MSI2 was silenced." (PMID 39990676, 2025). "Tumor spheres isolated from Msi2+ cells after quaternary passage in vitro and transplanted in vivo form highly aggressive flank tumors (C) that retain Msi2 expression (D) and are able to metastasize to the lung (E)." (PMID 40047406, 2025). "(B) Msi2-expressing cells isolated from KP lung epithelia following tamoxifen treatment preferentially form tumor spheres over multiple cell passages in vitro as compared to non-expressing cells." (PMID 40047406, 2025). "The expansion of Msi2 expression in lung tumors compared to normal lung epithelia suggests that normal cells expressing Msi2 are more sensitive to transformation, or that once transformed, Msi2 expression is amplified in tumor cells." (PMID 40047406, 2025). "In PDAC, MSI2 is substantially up-regulated and functionally validated to enhance tumor growth and metastasis in both ex vivo and in vivo models." (PMID 41049614, 2025). "Studies have confirmed that MSI2 expression is increased in most solid tumors and is crucial for tumor proliferation." (PMID 39969091, 2025). "MSI2 plays a role in promoting tumor invasion and metastasis, consistent with the findings described previously." (PMID 38645664, 2024). "The interaction of RNA‐binding motif protein 17 (RBM17) with MSI2 was identified through immunoprecipitation‐mass spectrometry (IP‐MS), revealing its involvement in DNA damage repair and tumor development." (PMID 38645664, 2024). "Taken together, our work is the first to investigate the molecular mechanism of MSI2 in tumor immune infiltration and immunometabolism in CRC." (PMID 38347600, 2024). "Previous studies have reported that MSI2 is an important marker of tumor progression and is vital for tumor metastasis, proliferation, and cell cycle in different types of tumors, including HCC." (PMID 38630658, 2024).
tumor (continued). "Recent studies have shown that MSI2 is closely related to tumor cell proliferation, invasion, migration, and apoptosis, and is an important regulator of various signaling pathways." (PMID 38630658, 2024). "Recent studies have indicated that MSI2 has gained considerable traction in the context of immune responses and tumor metabolic processes." (PMID 38347600, 2024). "To explore the ferroptosis effect of MSI2 on CRC, we first analyzed MSI2 expression through the TCGA CRC datasets via the GEPIA tool and found that the transcript level of MSI2 was higher in tumor tissue than in normal tissue." (PMID 38041016, 2023). "To further substantiate the increased MSI2 gene and protein in NSCLC patients, we analyzed and confirmed the high MSI2 expression in matched tumor and normal tissues obtained from LUSC and LUAD patients (GSE31552)." (PMID 37941042, 2023). "Total liver weight changes were consistent with the marked inhibitory effect realized by targeting both Adar1 and Msi2 or by re-expressing Slc38a4, as indicated by the in vivo tumor load." (PMID 36599932, 2023). "And the migration and invasion of tumor cells were markedly suppressed after MSI2 knockdown in SW620 and LOVO stable cells but significantly promoted in HT29 stable cells upon MSI2 overexpression." (PMID 38041016, 2023). "The MSI2 gene is involved in intestinal and hematological stem cell pathways and promotes tumor progression, dissemination and drug resistance in several solid and hematological malignancies." (PMID 37107676, 2023). "Immunohistochemical analysis of tumor tissues showed that modulation of MSI2 in tumor cells had a direct relationship to MYC expression level." (PMID 37117191, 2023). "HEL group, indicating that overexpression of MSI2 can promote hematopoietic tumor cells to infiltrate into other organs and tissues." (PMID 37149661, 2023). "MSI2 knockdown decreased the expression of genes related to apoptosis and stem cell features and significantly reduced clonogenic growth, tumor cell survival and chemoresistance in MCL cells." (PMID 36509891, 2023). "We found that larger sizes and heavier weights of tumor and spleen and liver appeared in the MSI2-OE." (PMID 37149661, 2023). "Currently, data describing the effects of MSI2 on tumor initiation and progression have been extensively explored." (PMID 38041016, 2023). "Taken together, our results unraveled that LIN28 inhibited Hippo pathway via recruiting MSI2 and de-stabilizing the mRNA transcript of YAP1 upstream kinases in TNBC cells, thereby enhancing CSC-associated properties, tumor cell growth and metastasis." (PMID 35102250, 2022). "The mRNA-binding proteins Msi1 and Msi2 have been most comprehensively characterised in murine PDAC as CSC markers that also enhance tumour-initiating capacity." (PMID 36088504, 2022). "Combination therapy demonstrated activity in vivo, since MSI2 depletion resulted in a 50% reduction of tumor growth which was further reduced with the addition of PRMT5 inhibitor (80% drop) without inducing toxicity." (PMID 36167829, 2022). "Consistent with their roles as tumour drivers, Msi2 and HuR are strong promoters of stem cell proliferation and inhibitor of differentiation." (PMID 34877814, 2022). "Functionally, we found knockdown of MSI2 in CAL51 cells dramatically reduced the tumor sphere growth, cell migration/invasion abilities." (PMID 35102250, 2022). "Accordingly, co-upregulations of LIN28 and MSI2 in TNBC tissues were strongly associated with YAP1 protein level and tumor malignance." (PMID 35102250, 2022). "Nude mouse subcutaneous tumorigenesis showed that SOX2-OT downregulation decreased the tumorigenicity of HCC, and affected the levels of miR-143-3p and MSI2 mRNA in tumor tissues." (PMID 34322386, 2021). "Consistent with our in vitro observations, the depletion of MSI2 in this model significantly reduced tumor growth, and significantly enhanced the anti-tumor effect of erlotinib." (PMID 33723247, 2021).
tumor (continued). "Overall, these data suggested MSI2 has a complex action in CRC that varies dependent on tumor stage." (PMID 34237057, 2021). "MSI2 alteration also promoted the transformation of intestinal cells into tumor cells by acting as a pleiotropic inhibitor of various known intestinal tumor suppressors, such as PTEN." (PMID 32448269, 2020). "We also found that in patients with NF1-MPNST with lung metastasis, MSI2 was highly expressed in comparison to primary tumours, where CAV1 expression was the opposite; CAV1 expression was low in lung metastases and high in primary tumours." (PMID 32606289, 2020). "We identified inositol‐3‐phosphate synthase 1 (ISYNA1) as a novel tumour suppressor regulated by MSI2." (PMID 32779876, 2020). "MSI1 and MSI2 are highly expressed in various tumours such as glioma, breast cancer, pancreatic cancer, colon cancer, lung cancer, ovarian cancer and prostate cancer." (PMID 32606289, 2020). "We explored the roles of MSI2 and Notch1 signaling in CD44v6+ LCSCs by sphere formation assay, transwell assay, clone formation assay in vitro, and xenograft tumor models in vivo." (PMID 31888685, 2019). "In vivo, the effect of MSI2 knockdown on CD44v6+ cells was examined in a mouse orthotopic liver xenograft tumor model and subcutaneous xenograft tumor model in NOD/SCID mice." (PMID 31888685, 2019). "The analysis revealed that MSI2 mRNA expression correlates with tumor grading and males show a higher level of MSI2 mRNA expression when compared to female patients." (PMID 31878037, 2019). "Compared with the shScr group, the shHMGA2 group displayed significant reductions in tumour size, while these changes were reversed in the shHMGA2 + MSI2 group." (PMID 31053152, 2019). "The interference efficiency of MSI2 shRNA1 was higher than that of MSI2 shRNA 2 and was used in the mouse orthotopic liver xenograft tumor model." (PMID 31888685, 2019). "The results showed that the expression of CD44v6 and MSI2 in HCC tissues was significantly higher than those in peri-tumor tissues." (PMID 31888685, 2019). "In line with the results in cell level, Numb protein expression in subcutaneous tumor of MSI2-shRNA groups is significantly higher than that in scramble groups (P<0.01)." (PMID 27092875, 2017). "Usingthis classification, we found that Msi2 was highly expressed inLuminal tumors.Msi1 was more variable across tumor subtypes, often showing abimodal profile, split between up- and down-regulation." (PMID 25380226, 2014). "In conclusion, we have identified >280 proteins that associate with SOX2 in DAOY MB tumor cells and demonstrate that two of the SOX2-associated proteins, MSI2 and USP9X, play key roles in the growth of MB and GB cells." (PMID 23667531, 2013). "For this purpose, we initially infected U87 GB tumor cells with the same MSI2 shRNA lentiviral vectors described earlier." (PMID 23667531, 2013). "Recent studies have shown that elevating Msi2 helps in the maintenance of hematopoietic and tumor stem cells." (PMID 22496868, 2012). "Importantly, loss of Msi2 led to a significant decrease (75%) in tumorsphere formation in vitro, suggesting that Msi2 is required for tumor cell propagation." (PMID 40047406, 2025). "Similarly, the sizes of the tumors excised from the euthanized mice showed that the MSI2-silenced MDA-MB-231-injected group had the highest tumor load among all the groups, whereas the MSI2-knockdown clone #1 tumor-bearing group had the lowest tumor load." (PMID 39990676, 2025). "Moreover, the downregulation of ELK4 decreased Ki67 expression in tumor tissues, and the overexpression of MSI2 reversed this effect." (PMID 39969091, 2025). "(C–E) Tumor spheres formed by Msi2+ cells in vitro form aggressive tumors in vivo." (PMID 40047406, 2025).